HNMT (histamine N-methyltransferase)
Diseases named in the same sentence as HNMT in open-access papers:
HNMT is named in the same sentence as 61 diseases in open-access papers, as found by Europe PMC text mining. Sharing a sentence is not in itself a finding about the gene and the disease. The quoted sentences say what the papers report.
breast carcinoma (7 papers, 2014 to 2025). "However, although HNMT has been demonstrated to be associated with breast cancer and liver cancer, little is known about its potential role in prostate cancer, making it another potential novel marker." (PMID 29344347, 2018). "In summary, our present study found for the first time that the variants of rs7164386 genotypes of HDC gene are significantly associated the risk of breast cancer while polymorphisms of HNMT and HRH3 might be irrelevant with breast cancer in Chinese Han populations." (PMID 24835231, 2014). "High histamine-N-methyltransferase (HNMT) expression has been noted in patients with ductal breast cancer compared with healthy controls." (PMID 35163585, 2022). "The aim of this study is to analyze the clinical associations of polymorphisms in HDC, HNMT and HRH3 with breast cancer." (PMID 24835231, 2014). "We found that polymorphisms of HNMT and HRH3 were irrelevant with breast cancer in the present study." (PMID 24835231, 2014). "Therefore, with respect to the notion that genetic factors contribute greatly to the risk and development of breast cancer, polymorphisms of HDC, HNMT, HRH3 and HRH4 are likely to be also associated with breast cancer risk." (PMID 24835231, 2014). "Another gene found to be overexpressed in tumor tissues is HNMT; however, a study on a Chinese Han population underscored the significance of histidine decarboxylase gene (HDC) polymorphisms, rather than those of the HNMT gene in breast cancer, further highlighting HDC’s importance in this disease." (PMID 39267843, 2024). "Therefore, genes that encode HDC, HNMT and HRH3 are rationally considered as candidate genes associated with development of breast cancer that is believed to be a multiple gene-related disease and whose development was previously reported to be affected by these molecules." (PMID 24835231, 2014). "However, the associations between polymorphisms of HDC, HNMT, HRH3 and susceptibility to breast cancer are still unknown so far and need to be elucidated." (PMID 24835231, 2014). "A literature search revealed that histamine N-methyltransferase (HNMT) mRNA was highly expressed in 83% of breast cancer cell lines (BCLs) (31 BCLs), especially HER2 + BCL, but not in the normal breast epithelial cell line MCF-10A." (PMID 39789599, 2025). "Additionally, one of the histamine catabolic enzymes, histamine N-methyltransferase (HNMT), and histamine H3 (HRH3) and H4 (HRH4) receptors were also closely involved in proliferation and differentiation of breast cancer according to recent investigations." (PMID 24835231, 2014).
asthma (5 papers, 2010 to 2025). "Our results indicate modifying influence of histamine N-methyltransferase functional polymorphism on the risk of asthma." (PMID 21040557, 2010). "The main finding of this study is an association of 314C/T polymorphism of HNMT gene with asthma in the Polish population of pediatric patients which may confirm that impaired histamine metabolism caused by reduced activity of HNMT is involved in asthma pathogenesis." (PMID 21040557, 2010). "We also found histamine N-methyltransferase (HNMT), a key protein in histidine metabolism, involved in the airways epithelium in asthma and rhinitis." (PMID 28598986, 2017). "The aim of our study was to analyze a relationship between the polymorphisms of two genes encoding histamine metabolizing enzymes (HNMT and ABP1) with the predisposition to asthma in the Polish population of pediatric patients." (PMID 21040557, 2010). "The other HNMT polymorphisms and ABP1 functional polymorphism seem unlikely to affect the risk of asthma." (PMID 21040557, 2010). "For other polymorphisms for HNMT and ABP1 genes, we have not observed relationship with asthma although the statistical power for some SNPs might not have been sufficient to detect an association." (PMID 21040557, 2010).
Parkinson disease (5 papers, 2015 to 2023). A progressive degenerative disorder of the central nervous system characterized by loss of dopamine producing neurons in the substantia nigra and the presence of Lewy bodies in the substantia nigra and locus coeruleus. "Clinical studies have suggested that single nucleotide polymorphisms of the human HNMT gene are associated with several brain disorders such as Parkinson’s disease and attention deficit hyperactivity disorder." (PMID 30744146, 2019). "Recent clinical studies have suggested that HNMT polymorphisms and associated changes in enzyme activity mediate pathological aspects of Parkinson’s disease and multiple sclerosis." (PMID 29162912, 2017). "Finally, future works should examine the importance of HNMT in rodent models of neurodegenerative diseases such as Alzheimer’s disease and Parkinson’s disease." (PMID 29162912, 2017).
Intellectual disability (4 papers, 2021 to 2024). "Only HNMT is disease-associated, specifically with a recessive type of intellectual disability (OMIM # 616739)." (PMID 38318288, 2023). "A more recent study identified a HNMT homozygous stop mutation (p.Gln30Stop) in an adolescent male patient with severe intellectual disability from a consanguineous family." (PMID 36292569, 2022). "Case report: male patient with a rare, mis-sense mutation in HNMT associated with a severe intellectual disability." (PMID 34335160, 2021). "Indeed, two novel mutations in the human HNMT gene (G179A and T632C) impairing its enzymatic activity had been associated with intellectual disability." (PMID 38541885, 2024).
diabetes (3 papers, 2010 to 2025). "The purpose of our study was to investigate the association between rs4885322 single-nucleotide polymorphism (SNP) of the UCHL3 gene and rs11558538 SNP of the HNMT gene with the risk of DR in Greek patients with type 2 diabetes mellitus (T2DM)." (PMID 40002753, 2025). "The importance of fatty liver was particularly striking among the top 30 diabetes-associated proteins (e.g. HGF, IGSF3, IL1RA, ALDH1A1, HNMT, ERBB2 and CDCP1)." (PMID 33279861, 2021). "API5, EDIL3, BFSP2, HNMT, and SCYL1BP1 were also among the top signals from the single-marker analysis within their associated region, but there is no clear connection currently between these genes and diabetes or its complications." (PMID 20871662, 2010).
lung carcinoma (3 papers, 2022 to 2023). "Our study adds to existing evidence for a miR-3065′s role as an oncosuppressor that interacts with HNMT in lung cancer." (PMID 35163585, 2022). "CCK8 and colony formation assay revealed that the knockdown of HNMT can remarkably weaken the cell proliferation ability of lung cancer cells." (PMID 36591493, 2022). "Moreover, further experiments indicated that HNMT was overexpressed and can enhance the proliferation ability in lung cancer cells." (PMID 36591493, 2022). "The qRT-PCR of cell lines indicated that HNMT was overexpressed in lung cancer cells." (PMID 36591493, 2022).
schizophrenia (3 papers, 2011 to 2018). A major psychotic disorder characterized by abnormalities in the perception or expression of reality. "The region contains potential susceptibility genes for schizophrenia, like HNMT (Histamine N-methyltransferase) and NR4A2 (alias NURR1, nuclear receptor subfamily 4, group A, member 2, an orphan nuclear receptor and putative transcription factor for the dopamine transporter)." (PMID 21897869, 2011). "Likewise, the detection of a link between schizophrenia-related sleep disorders and genes implicated in neurotransmitter metabolism (TH and HNMT) and signal transduction (GNB3 and BTBD9) emphasizes the central role of neurotransmission disturbances in the emergence of schizophrenia symptomatology." (PMID 29587340, 2018).
allergic asthma (2 papers, 2010 to 2019). A asthma with a basis in a pathological type I hypersensitivity reaction. "In conclusion, we report here an association of HNMT functional polymorphism with allergic asthma which was further confirmed on a larger group of independent studies." (PMID 21040557, 2010).
allergic disease (2 papers, 2022 to 2025). An immune response that occurs following re-exposure to an innocuous antigen, and that requires the presence of existing antibodies against that antigen. "Studies on DAO/HNMT deficiency or increased serum histamine levels are associated with allergic diseases (such as AD, allergic rhinitis, or asthma), and the severity of bronchial hyper-responsiveness supports this view." (PMID 35327646, 2022). "A number of studies have investigated the relationship between SNPs in the HNMT gene and allergic diseases in children." (PMID 35327646, 2022).
Anxiety (2 papers, 2012 to 2017). Intense feelings of nervousness, tension, or panic often arise in response to interpersonal stresses. "It is believed that the decreased levels of brain histamine, which are associated with a functional polymorphism of histamine N-methyltransferase (HNMT) called Thr105 allele, may result in higher levels of anxiety." (PMID 22984571, 2012).
atopic dermatitis (2 papers, 2020 to 2022). "A study demonstrated that miR-223 might indirectly upregulate HNMT expression in atopic dermatitis pathogenesis." (PMID 35163585, 2022).
bladder cancer (2 papers, 2015 to 2019). "Although unreported in bladder cancer, reduced HNMT transcription has been reported in other human carcinomas and is posited to be involved in tumorigenesis." (PMID 26401343, 2015).
colon adenoma (2 papers, 2018 to 2021). An adenoma that arises from the colon. "The same working group was able to show that not only DAO activity, but also – and even to a greater extent – HNMT activity was diminished in the affected tissue of patients with colonic adenoma." (PMID 34651098, 2021).
acute kidney injury (1 paper, 2022). Sudden and sustained deterioration of the kidney function characterized by decreased glomerular filtration rate, increased serum creatinine or oliguria. "Core body temperature and plasma histamine levels were not significantly different between wild type (WT) and DAO KO mice after oral and subcutaneous histamine challenge with and without acute kidney injury or administration of HNMT inhibitors." (PMID 35303133, 2022).
autism spectrum disorder (1 paper, 2021). A spectrum of developmental disorders that includes autism, and Asperger syndrome. "Histamine dysregulation may have a role in mediating autism spectrum disorder phenotype with altered expression of key histamine signaling genes HNMT, HRH1, HRH2, and HRH3 in post-mortem brains of patients with ASD." (PMID 34335160, 2021).
breast tumor (1 paper, 2025). "HNMT protein levels in TMAs containing human breast tumor tissue (n = 211) were evaluated by IHC staining analysis." (PMID 39789599, 2025). "Based on the analysis of breast tumor tissue, it is evident that in the case of high expression of HNMT protein (case 1), HER2-ICD was detected in the cytoplasm (stained in green) along with an equivalent amount of HER2 extracellular domain (HER2-ECD, stained in brown)." (PMID 39789599, 2025).
endometriosis (1 paper, 2025). The growth of functional endometrial tissue in anatomic sites outside the uterine body. "However, our MR analysis suggested that decreased expression levels of HNMT and CCDC28A were associated with an increased risk of developing endometriosis." (PMID 40140093, 2025).
esophageal squamous cell carcinoma (1 paper, 2022). Esophageal squamous cell carcinoma (ESCC) is a type of esophageal carcinoma (EC) that can affect any part of the esophagus, but is usually located in the upper or middle third. "A microarray-based study on esophageal squamous cell carcinoma determined that HNMT is one of the crucial players in controlling signal transduction networks." (PMID 35163585, 2022).
gastric cancer (1 paper, 2021). A primary or metastatic malignant neoplasm involving the stomach. "Finally, we found that the imbalance of 11 immune regulatory factors could predict the overall survival time of gastric cancer, including EZH2, NRP1, CD59, OsBPL1aBCL11B, BASP1, HNMT, CXCR4, ASGR2, ANXA5, CDH2." (PMID 34322132, 2021).
insomnia (1 paper, 2018). A sleep disorder characterized by difficulty in falling asleep and/or remaining asleep. "Antipsychotic-induced restless legs syndrome was linked to polymorphisms located on CLOCK, BTBD9, GNB3, and TH genes, clozapine-induced somnolence was correlated with polymorphisms of HNMT gene, while insomnia was associated with variants of the MTNR1 gene." (PMID 29587340, 2018).
migraine (1 paper, 2023). "A prior study investigating the possible association between functional single nucleotide polymorphisms in the DAO gene in the chromosome 7q36.1 with the risk for migraine reported a lack of association between Thr105Ile SNP (rs1801105) polymorphism in the HNMT gene located at chromosome 2q22.1." (PMID 36979637, 2023).
motion sickness (1 paper, 2021). sympton caused by motion, as sea sickness, train sickness, car sickness, air sickness, or space motion sickness. "In addition, inhibition of histamine N-methyltransferase (HNMT), the enzyme responsible for metabolism of histamine with tacrine, increases endogenous histamine and exacerbates motion sickness in dogs, as well as susceptibility to condition taste aversion (an index of motion sickness) in rats." (PMID 34071460, 2021).
prostate carcinoma (1 paper, 2018). A carcinoma that arises from epithelial cells of the prostate gland. "In addition, based on our qPCR analysis, HNMT gene expression was reduced by 6.67-fold, which supports the likelihood of a role of HNMT in prostate cancer." (PMID 29344347, 2018).
retinal degeneration (1 paper, 2024). Degeneration of the retina. "Further, expressing HNMT, a mammalian enzyme that degrades histamine, suppressed the retinal degeneration associated with mislocalized Hdc." (PMID 39242788, 2024).
somnolence (1 paper, 2018). "Additionally, a correlation was revealed between clozapine-induced somnolence and rs2737385 polymorphism on HNMT gene, rs1552498 and rs17034063 polymorphisms on HRH1 gene (Histamine Receptor H1), as well as rs697738 polymorphism on AOC1 gene (Amine Oxidase Copper Containing 1)." (PMID 29587340, 2018).
cancer (13 papers, 2010 to 2025). A tumor composed of atypical neoplastic, often pleomorphic cells that invade other tissues. "Further cell experiments confirmed the association between HNMT overexpression and the malignancy of cancer cell metastasis." (PMID 39789599, 2025). "In addition, HNMT upregulation causes cancer stem cell formation and protect it from oxidative stress by interaction with HER2 in NSCLC." (PMID 36618700, 2022). "Conversely, Kuo and colleagues found that patients with NSCLC who have low miR-223 levels had higher histamine N-methyltransferase (HNMT) expression in cancer tissue (compared to normal tissue) and a worse prognosis than those with low HNMT and higher miR-223 expression in their cancer tissue." (PMID 39125761, 2024). "To evaluate whether HNMT also played a role in the origin of cancer stemness in NSCLC, we first assessed the colony formation ability of H441 with HNMT knockdown and of CL1-0 with HNMT overexpression." (PMID 35163585, 2022). "In this study, we elucidated the role of HNMT in cancer, specifically in NSCLC carcinogenesis." (PMID 35163585, 2022). "Therefore, we employed a high concentration (100 μM) of SKF-91488 to observe whether inhibiting HNMT enzyme activity affects the growth of cancer cells." (PMID 39789599, 2025). "Higher levels of cytoplasmic HNMT (detected by HNMT-specific antibody, stained green) and membranous HER2 (detected by trastuzumab, stained brown) proteins were detected in the cancer cells of all responder tumor sections." (PMID 39789599, 2025). "The Cancer Genome Atlas (TCGA) and Cancer Cell Line Encyclopedia (CCLE, Expression Public 22Q4) databases also showed that HNMT mRNA was detected higher in a HER2 + subgroup." (PMID 39789599, 2025). "These histamine receptors interact with proteins, such as HNMT and LYN, suggesting a complex regulatory mechanism involving histamine signaling in cancer progression." (PMID 39267843, 2024).
tumor (6 papers, 2015 to 2025). "The results from the TCGA database showed that high expression of HNMT mRNA in tumor tissues was associated with poorer prognosis in BC patients." (PMID 39789599, 2025). "Higher HNMT protein expression levels in the tumor tissues of BC patients were associated with poorer 10-year overall survival." (PMID 39789599, 2025). "We validated HNMT protein expression levels in BCLs and human BC tumor tissues with known clinical parameters to test this observation." (PMID 39789599, 2025). "The analysis results from the TCGA database also showed that HNMT mRNA expression was higher in the tumor tissues of HER2 + BC patients than in TNBC BC patients (P < 0.001)." (PMID 39789599, 2025). "Subsequent univariate (UA) and multivariate analysis (MA) was used to evaluate the significance of the expression of HNMT and Her2, age, gender, tumor size, LNM, clinical-stage, subtypes on NSCLC-specific survival." (PMID 35163585, 2022). "Based on these data, we hypothesized that both HER2 and HNMT are overexpressed in the tumor tissue of patients who respond to trastuzumab." (PMID 39789599, 2025). "However, the underlying mechanism remains unclear, and this study inspired us to confirm whether HNMT expression in TNBC tumor tissue can be used as a molecular marker to identify patients who respond to anti-HER2 ACD (T-Dxd) therapy." (PMID 39789599, 2025). "We next asked whether HNMT overexpression affects HER-2-mediated tumor aggressiveness." (PMID 39789599, 2025). "Kuo and their colleagues found that the upregulation of HNMT could induce tumor stemness in NSCLC." (PMID 36591493, 2022). "Other genes such as LRRC8E, HNMT, and RFC2 were downregulated in the tumor buds but upregulated in the microenvironment." (PMID 28687755, 2017). "In the T > N ​​group, HNMT mRNA expression in tumor cells was significantly higher (20.58-fold) than that in normal cells." (PMID 39789599, 2025). "Real-time PCR was used to determine HNMT mRNA levels in 766 human tissue sample pairs (tumor vs. normal)." (PMID 39789599, 2025).
neurological diseases (2 papers, 2021 to 2022). "Although recent findings suggest a possible relation between HNMT activity and neurological disorders, the impact of changes in HNMT activity in disease onset and progression is yet to be identified." (PMID 34680041, 2021).
neurodevelopmental disorder (1 paper, 2022). A behavioral and cognitive disorder with onset during the developmental period that involves impaired or aberrant development of intellectual, motor, or social functions. "Two additional studies reported heterozygous deleted CNV encompassing the HNMT gene in patients affected by neurodevelopmental disorders." (PMID 36292569, 2022).
HNMT also shares sentences with these, for which no sentence is quoted: Alzheimer disease (2 papers); brain disorder (2); type 2 diabetes (2); alcoholism (1); allergic rhinitis (1); Allergy (1); amblyopia (1); astrocytomas (1); attention deficit-hyperactivity disorder (1); Blindness (1); Chronic Heart Failure (1); chronic renal failure (1); CNS cancer (1); cocaine addiction (1); diabetic retinopathy (1); food allergy (1); Graves disease (1); hepatocellular carcinoma (1); Hyperammonemia (1); Hypertension (1); inflammatory bowel disease (1); injury (1); liver cancer (1); malaria (1); neurodegenerative disease (1); Obesity (1); restless legs syndrome (1); rheumatoid arthritis (1); rhinitis (1); secondary progressive multiple sclerosis (1).
A further 2 diseases each share a sentence with HNMT in 1 paper.